IQGAP1 (IQ motif containing GTPase activating protein 1)
Diseases named in the same sentence as IQGAP1 in open-access papers (continued):
Sharing a sentence is not in itself a finding about the gene and the disease.
infection (16 papers, 2009 to 2025). The state of being infected such as from the introduction of a foreign agent such as serum, vaccine, antigenic substance or organism. "We also found that PI3K signaling was highly induced in oral keratinocytes upon MmuPV1 infection, which was attenuated in IQGAP1-deficient cells." (PMID 34068608, 2021). "With the knowledge that MmuPV1 induces PI3K signaling in an IQGAP1-dependent mechanism in vitro, we next investigated the role of IQGAP1 in PV-associated head and neck tumorigenesis in vivo using the MmuPV1 infection model we previously established." (PMID 34068608, 2021). "In this study, we showed for the first time that deletion of one IQGAP1 allele in mice significantly promotes the development of high grade dysplasia in response to infection with pro-carcinogenic H. pylori strains." (PMID 27729612, 2016). "Therefore, we decided to study the role of IQGAP1 in PV-associated head and neck tumorigenesis using a newly developed MmuPV1-infection based murine model for HNSCC." (PMID 34068608, 2021). "One explanation for the disparity with the findings in the MmuPV1 infection model compared to the HPV16 transgenic model is that IQGAP1 contributes more to earlier stages of PV-associated carcinogenesis, which can be captured by the MmuPV1-infection model, but not the HPV16-transgenic mouse model." (PMID 34439095, 2021). "This is entirely consistent with its role in filopodial formation but also its augmentation by HIV Gag-IQGAP1 during infection." (PMID 35056004, 2022). "In macrophages, IQGAP1 interacts with the actin nucleating protein, diaphanous-related formin (Dia1), to take part in phagocytosis and phagocytic cup formation during infection." (PMID 36341336, 2022). "In order to study the role of IQGAP1 in papillomavirus-associated HNSCC in a physiologically relevant scenario, we turned to an infection-based model for HNSCC using the mouse papillomavirus (MmuPV1) that was recently developed in our lab." (PMID 34439095, 2021). "In this work, we show that CiaD binds to the host cell protein IQGAP1 to displace RacGAP1 using affinity pull-down experiments coupled with LC–MS/MS and immunoblots, yeast-two hybrid (Y2H), and C. jejuni-host cell infection assays." (PMID 33637714, 2021). "PI3K signaling was also highly activated in keratinocytes upon in vitro infection with a murine papillomavirus, MmuPV1, at least partly through a mechanism dependent on IQGAP1." (PMID 34068608, 2021). "IQGAP1 was necessary for optimal PI3K signaling induced by HPV16 oncoproteins in transgenic mice and MmuPV1 infection, a mouse papillomavirus that causes HNSCC in mice." (PMID 34068608, 2021). "infection leads to a progressive shift of IQGAP1 from cytoplasmic expression to cell surface expression." (PMID 27729612, 2016). "The same trends were obtained with AGS cells in which IQGAP1 was mainly expressed in the cytoplasm and to a lesser extent at the cell-cell junctions and was translocated after infection to the plasma membrane." (PMID 27729612, 2016). "As IQGAP1 is a component of adherens junctions and as these structures are destabilized following infection, the impact of IQGAP1 knock-down on H. pylori-promoted-EMT and CSC properties was evaluated." (PMID 27729612, 2016). "Activation of mTOR during infection depended on IQGAP1, since S6K phosphorylation remained at baseline in IQGAP1-/- MEFs." (PMID 26473364, 2015). "In immunofluorescence analysis, MARV-infected IQGAP1-depleted cells were characterized by accumulations of nucleocapsids in the cell periphery similar as observed with Tsg101 depletion or rMARVPSAPmut infection (see white arrows)." (PMID 25330247, 2014). "Nevertheless, the effects of SseI on host cell migration, through its interactions with the host molecule IQGAP1, correlate with a reduced capacity of the host to clear S. typhimurium from systemic sites of infection." (PMID 19956712, 2009).
infection (continued). "SseI directly binds IQGAP1 in primary macrophage and DC lysates and during Salmonella-infection of primary macrophages." (PMID 19956712, 2009). "MmuPV1 infection has been found to elevate the protein abundance of IQGAP1 in mice." (PMID 41165329, 2025). "Both infection with WT strains and transfection with pCMV-ompA plasmid inhibited the interaction between IQGAP1 and F-actin; they also promoted the interaction between IQGAP1 and β-catenin, thus inducing the dissociation of α-catenin from the E-cadherin–catenin complex." (PMID 35844614, 2022). "This indicates that MmuPV1 can induce PI3K signaling upon infection in an IQGAP1-dependent manner." (PMID 34068608, 2021). "Quantitative PCR (qPCR) analysis of DNA extracted from oral swabs collected at 3 weeks post-infection showed that both MmuPV1-infected Iqgap1+/+ and Iqgap1−/− mice carried similar copy numbers of the virus, indicating that IQGAP1 had no measurable effect on incidence of MmuPV1 infection in mice." (PMID 34439095, 2021). "Importantly, this finding shows that the native C. jejuni protein interacts with IQGAP1 during the course of normal cellular infection." (PMID 33637714, 2021). "The purpose of the infection experiments was to test whether the CiaD protein was binding to IQGAP1 during cellular infection." (PMID 33637714, 2021). "At 1 hr of infection of IQGAP1+/+ MEFs, WT or ospB complemented S. flexneri induced more phosphorylation of S6K than the ospB mutant, indicating that OspB delivered by S. flexneri activates mTOR early during infection." (PMID 26473364, 2015). "Furthermore, we demonstrated that S. typhimurium infection induced IQGAP1-independent pathways of cell migration, which was dependent on infection with intact bacteria (as infection with heat-killed bacteria did not induce migration)." (PMID 19956712, 2009). "However, we found that the association of RacGAP1 with IQGAP1 was reduced approximately 50% upon infection with a C. jejuni wild-type strain but not upon infection with a ∆ciaD mutant (p < 0.05)." (PMID 33637714, 2021). "With the newly developed MmuPV1 infection-based HNSCC model, more studies can now be conducted to understand the role of IQGAP1 and IQGAP1-mediated signaling at different stages of PV pathogenesis." (PMID 34068608, 2021). "Using confocal imaging and immunoblotting, we observed that the F-actin was disrupted and the expression and distribution of IQGAP1 and AQP6 were reduced upon Hazara infection." (PMID 29209610, 2017). "Consistent with this scenario, P.aeruginosa relies on alterations of membrane properties at the leading edge (PI3K, Rac1, IQGAP1 and actin) for the insertion and function of type III secretion translocon and to establish an infection." (PMID 23071436, 2012). "Contrary to our results from the MmuPV1 infection-based model, we did not observe any significant contribution of IQGAP1 to carcinogenesis in this HPV16 transgenic mouse model." (PMID 34068608, 2021). "Neither Iqgap1+/+ nor Iqgap1−/− mice infected with MmuPV1 displayed a difference in infection incidence at 3 weeks post-infection, indicating that IQGAP1 protein most likely did not affect viral infectivity." (PMID 34068608, 2021). "We found that there was nearly no activation of either Rac1 and Cdc42 in the IQGAP1 knockdown cells, while there was robust activation of both Rac1 and Cdc42 in the cells expressing the non-targeting shRNA during infection." (PMID 33637714, 2021). "We demonstrate that the effector protein OspB interacts directly with the scaffolding protein IQGAP1, and that the absence of either OspB or IQGAP1 during infection leads to larger areas of S. flexneri spread through cell monolayers." (PMID 26473364, 2015). "However, in contrast to our study, there was a lack of Erk 1/2 activation in IQGAP1 knockout cells upon infection with Salmonella63." (PMID 33637714, 2021).
infection (continued). "As Shigella spread through monolayers occurs by actin based motility, we compared several parameters relating to this process during infection of IQGAP1-/- versus IQGAP1+/+ MEFs, but found only small differences that did not appear to fully explain the observed differences in spread." (PMID 26473364, 2015). "We have shown that while infection with live bacteria that are lacking sseI induced macrophage migration, infection with SseI-expressing bacteria blocked directed migration in an IQGAP1-dependent manner, demonstrating a functional interaction between SseI and IQGAP1." (PMID 19956712, 2009). "Thus, infection with intact bacteria induced migration that was independent of IQGAP1 and SseI." (PMID 19956712, 2009). "qPCR showed that IQGAP1 depletion prevented the upregulation of IL-6 and TNF-α induced by infection with the WT strains but did not affect IL-6 and TNF-α expression in the ΔompA strain-infected groups." (PMID 35844614, 2022).
adenocarcinoma (3 papers, 2000 to 2026). A common cancer characterized by the presence of malignant glandular cells. "In all 20 cases with well differentiated adenocarcinomas, α-catenin and IQGAP1 disappeared from the cell adhesive sites, but other cytoplasmic molecules were co-localized with E-cadherin along the cell boundaries." (PMID 11027430, 2000). "In all 10 cases with poorly differentiated adenocarcinomas, E-cadherin and cytoplasmic molecules accumulated as large aggregates along cell adhesive sites, and the localization of IQGAP1 differed from those of other cytoplasmic molecules." (PMID 11027430, 2000).
metabolic disorders (3 papers, 2021 to 2025). "Recent research has shed light on the complex involvement of IQGAP1 in various metabolic diseases." (PMID 41035668, 2025). "Therefore, the IQGAP1-AMPK axis presents a potential target for therapeutic interventions in metabolic disorders." (PMID 41035668, 2025). "The data presented in this study that IQGAP1 binds AMPK and is required for maximum activation of AMPK raise the possibility that the interaction between AMPK and IQGAP1 could be a potential target for the development of new therapeutic agents for metabolic disorders." (PMID 33191271, 2021). "In the absence of IQGAP1, AMPK activation is impaired, leading to alterations in glucose homeostasis and lipid metabolism, key features of metabolic diseases like type 2 diabetes." (PMID 41035668, 2025).
peripheral neuropathy (1 paper, 2025). A disorder affecting the peripheral nervous system. "This positions IQGAP1 as a critical node in the neuro-glio-vascular unit dysfunction during chemotherapy-induced peripheral neuropathy and cilastatin as a potential modulator of these pleiotropic effects." (PMID 40862773, 2025).
IQGAP1 also shares sentences with these, for which no sentence is quoted: autism (2 papers); acute myeloid leukemia (1); acute promyelocytic leukemia (1); acute T cell leukemia (1); arteriosclerosis (1); Azoospermia (1); Chagas disease (1); cholangiocarcinoma (1); colon adenocarcinoma (1); depression (1); diabetic kidney disease (1); dry eye (1); endometrioid adenocarcinoma (1); epilepsy (1); focal and segmental glomerulosclerosis (1); head and neck squamous cell carcinoma (1); Helicobacter infection (1); hyperlipidemia (1); immune diseases (1); Insulin resistance (1); iris coloboma (1); ischemic disease (1); lung adenocarcinoma (1); minimal change disease (1); neuropathy (1); osteosarcoma (1); peripheral neurotoxicity (1); peripheral vascular disease (1); pertussis (1); preeclampsia (1).
A further 8 diseases each share a sentence with IQGAP1 in 1 paper.